PCA3 (prostate cancer associated 3)
Diseases named in the same sentence as PCA3 in open-access papers (continued):
Sharing a sentence is not in itself a finding about the gene and the disease.
prostate carcinoma (continued). "PRUNE2 has been reported to function as a tumor suppressor gene in prostate cancer, where prostate cancer antigen three (PCA3) regulates levels of PRUNE2 through formation of a PRUNE2/PCA3 double‐stranded RNA." (PMID 28881068, 2017). "Urinary prostate cancer associated 3 (PCA3) was also identified as a potential diagnostic indicator for prostate cancer, with upregulation of PCA3 in prostate cancer." (PMID 27999202, 2017). "PCA3 is a prostate-specific non-coding RNA that is highly overexpressed in prostate cancer compared to the normal prostate." (PMID 28912732, 2017). "Currently, one prostate cancer urine test measures a cancer-specific non-coding transcript PCA3 released from prostate cancer cells." (PMID 29254211, 2017). "The PCA3 lncRNA binds to the PRUNE2 pre-mRNA in prostate cancer cell lines (LNCaP and PC3), generating a double stranded RNA molecule and therefore regulating the expression of PRUNE2 at both mRNA and protein levels." (PMID 29203868, 2017). "Prostate cancer antigen 3 (PCA3) is the most notable example since it is a specific urine marker for prostate cancer." (PMID 28410618, 2017). "For example, lncRNA PCA3 has been identified as a useful invasive biomarker for the diagnosis of prostate cancer with a prognostic value." (PMID 29029437, 2017). "PCA3 has also a prognostic value for prostate cancer, since its expression levels correlate well with tumor aggressiveness." (PMID 28634418, 2017). "Prostate cancer antigen 3 (PCA3) is a prostate cancer-specific antigen mapped to chromosome 9q21-22." (PMID 28275218, 2017). "As a proof of concept, we analyzed the PCA3 STR in our large case-control cohort and found it to be significantly associated with prostate cancer risk, Gleason score, and all-cause mortality." (PMID 29203868, 2017). "A high urinary PCA3 score is correlated with a greater possibility of being diagnosed as prostate cancer on biopsy." (PMID 28272371, 2017). "In experimental models of human prostate cancer, PCA3 overexpression as well as PRUNE2 silencing accelerates the growth of tumor xenografts in vivo, while increasing cell proliferation, adhesion, and migration in vitro." (PMID 28751581, 2017). "We further suggest viral infection‐related mechanisms as functional in PCA3 overexpression and involved in prostate cancer initiation and/or progression." (PMID 28751581, 2017). "For example, prostate cancer antigen 3 (PCA3 or DD3) is a lncRNA that is highly overexpressed in prostate cancer." (PMID 26942882, 2016). "In the second example, we consider a prospective study conducted by the Early Detection Research Network aimed to assess a urine biomarker for prostate cancer, the Prostate Cancer Antigen 3 (PCA3) (Deras and others, 2008)." (PMID 26883772, 2016). "This is due in part to the observation that the 3STA not only amplified the PCA3 promoter activity, but also maintained its specificity for prostate cancer cells." (PMID 26594800, 2016). "In receiver operating characteristic curve (ROC) analysis, this result translated into an area under the ROC curve (AUC) of 0.75, further supporting PCA3 as a reasonable marker for prostate cancer diagnosis." (PMID 27189224, 2016). "A meta-analysis of several studies confirmed the validity of urine PCA3 levels for prostate cancer diagnosis, with a summary sensitivity of 62 % and a specificity of 75 %." (PMID 27189224, 2016). "For instance, the antisense lncRNA PCA3 is the most prominent and clinically relevant RNA biomarker in prostate cancer, which is overexpressed in > 95% of primary tumors." (PMID 27191265, 2016). "As its levels correlate with tumor aggressiveness as classified by the Gleason score, circulating PCA3 can also reflect the aggressiveness of prostate cancer." (PMID 27189224, 2016). "Among those with prostate cancer, PCA3 and PSA have mean 0.64 and 0.42, and variance 1.0 and 0.83, respectively." (PMID 26883772, 2016).
prostate carcinoma (continued). "The detection of PCA3 in the urine has been demonstrated to be a more specific marker to diagnose prostate cancer than the commonly used prostate-specific antigen (PSA) and already found wide application in clinics." (PMID 25954300, 2015). "PCA3 is reported to be localized to prostatic tissue and found in 95% of prostate cancer and prostate metastasis specimens." (PMID 26397728, 2015). "Prostate cancer antigen 3 (PCA3) and microRNA-141 (miR-141) are emerging molecules in prostate cancer (PCa) pathogenesis and have been shown to be involvedin androgen signaling." (PMID 25685739, 2015). "Detection of prostate cancer antigen 3 (PCA3) in urine is another emerging biomarker for prostate cancer." (PMID 26397728, 2015). "The lncRNA PCA3 is highly up-regulated in prostate cancer and is a potent biomarker detectable in urine." (PMID 26082843, 2015). "The study was conducted to determine the clinical utility of the prostate cancer gene 3 (PCA3) assay to predict biopsy-detected cancers in Chinese men." (PMID 26628213, 2015). "Some reports have demonstrated the use of lncRNA PCA3 as a specific and reliable marker detectable in urine samples from patients of prostate cancer, instead of the standardized use of the prostate-specific antigen (PSA)." (PMID 25338714, 2015). "Circulating PCA3 has also prognostic value for the evaluation of prostate cancer disease evolution, since its levels correlate with tumor aggressiveness as classified by Gleason score." (PMID 26516918, 2015). "In an ROC analysis, this translated to an AUC of 0.75, further supporting PCA3 as a reasonable marker for prostate cancer diagnosis." (PMID 26516918, 2015). "In 2009, Nilsson and coworkers demonstrated the presence of two known prostate cancer biomarkers, PCA-3 and TMPRSS2:ERG, in exosomes isolated from the urine of prostate cancer patients." (PMID 25695100, 2015). "The study evaluated the PCA3 assay as an additional tool in facilitating diagnosis of prostate cancer in Chinese men." (PMID 26628213, 2015). "The potential of circulating PCA3 as a biomarker for prostate cancer has been explored in several studies, which have quantified transcript expression in patients’ urine." (PMID 26516918, 2015). "siRNA mediated down-regulation of PCA3 significantly inhibited growth and viability of prostate cancer cells and also reduced the expression of AR target genes, suggesting it can be a potential therapeutic target." (PMID 26082843, 2015). "PCA3 has been included in a nomogram outperforming previous clinical models for the prediction of any prostate cancer (PCa) and high grade PCa (HGPCa) at the initial prostate biopsy (IBx)." (PMID 26362197, 2015). "The most prominent example of such biomarkers is PCA3, a lncRNA highly expressed is prostate cancer." (PMID 25954300, 2015). "A meta-analysis of several of these studies determined the validity of PCA3 levels in urine for prostate cancer diagnosis, with a summary sensitivity of 62% and specificity of 75%." (PMID 26516918, 2015). "For example, genomic mapping studies have identified lncRNA PCA3 as a prostate cancer specific gene; however, such clinical studies on the circulation lncRNA were never performed in HCC." (PMID 25714016, 2015). "Another study on human prostate cancer also suggested an involvement of TAAA tandem repeats as mediators of the expression of PCA3 gene." (PMID 25318583, 2014). "Data relating to the accuracy of prostate cancer staging are contradictory and PCA3 as a prognostic test should be subjected to further studies." (PMID 27351008, 2014). "The PCA3 gene is over-expressed in prostate cancer and has been shown to be a valuable biomarker for this disease." (PMID 24040105, 2013). "A common subtype of this fusion, in combination with urine PCA3, enhanced the predictive performance of serum PSA for prostate cancer risk and clinically relevant cancer on biopsy in a recent clinical study." (PMID 24133629, 2013).
prostate carcinoma (continued). "Here we demonstrate that the BMCC1-1 RNA is expressed in 10/10 PCA3 positive prostate cancer tissue samples." (PMID 24040105, 2013). "The ProgensaTM PCA3 urine test, a kit to detect PCA3 in urine samples from patients with prostate cancer is already being clinically used." (PMID 23887658, 2013). "We evaluated the ability of phi and PCA3 to identify prostate cancer (PCa) at initial prostate biopsy in men with total PSA range of 2–10 ng/ml." (PMID 23861782, 2013). "Recently, Prostate cancer antigen 3 (PCA3) and phi (prostate health index) have been proposed as useful tools in prostate cancer patient care." (PMID 23861782, 2013). "Prostate cancer derived urine exosomes are shown to contain two known prostate cancer biomarkers, PCA-3 and TMPRSS2: ERG, showing the potential for diagnosis and monitoring cancer patient’s status." (PMID 25419445, 2012). "Testing for elevated PCA3 has evolved into a quantitative urine test to facilitate prostate cancer diagnosis via non-invasive methodology." (PMID 22641253, 2012). "Since PC3 is a well-established cell-line model representing a more aggressive stage of prostate cancer tumors, our data provide additional evidence for a role of PCA3 in modulating PCa cell survival." (PMID 23130941, 2012). "The PCA3 assay identifies non-coding mRNA from the PCA3 gene that is overexpressed in prostate cancer." (PMID 20648010, 2010). "Other promising markers of prostate cancer, such as PCA3, have also been shown to enhance the discrimination of prostate cancer on biopsy; however, the improvements are smaller than those from the full kallikrein panel." (PMID 21092177, 2010). "PCA3 mRNA expression is elevated over 60-fold in prostate cancer tissues compared to benign tissues." (PMID 20598135, 2010). "TMPRSS2:ERG gene fusion mRNAs have been associated with aggressive prostate cancer morphology in tissues and a preliminary study using a combination of TMPRSS2:ERG plus PCA3 assays has shown synergistic diagnostic utility in urine specimens." (PMID 20598135, 2010). "As a proof-of-concept, we show the presence of two known prostate cancer biomarkers, PCA-3 and TMPRSS2:ERG the in exosomes isolated from urine of patients, showing the potential for diagnosis and monitoring cancer patients status." (PMID 19401683, 2009). "One of these has been shown to be overexpressed in PCa-PCA-3 and the other is a product of a chromosomal rearrangement, which creates a common prostate cancer-specific product, the TMPRSS2:ERG fusion." (PMID 19401683, 2009). "Although PCA3 has been proposed as an alternative to PSA for prostate cancer detection, its actual prognostic value is uncertain." (PMID 19002168, 2008). "The PCA3 mRNA expression is upregulated to an order of 70-fold in prostate cancer as compared to normal benign tissue." (PMID 19675766, 2007). "As even a minute number of PCA3 transcripts can be identified with RT-PCR, quantitative assays have a potential role in the diagnosis and molecular staging of prostate cancer." (PMID 19675766, 2007). "The PCA3 promoter has an important role in gene therapy as it is a very specific marker for prostate cancer." (PMID 19675766, 2007). "Measures the overexpression of the PCA3 gene, which is highly specific to prostate cancer cells." (PMID 41394863, 2025). "For example, PCA3 is a well-known prostate cancer-specific lncRNA." (PMID 40243658, 2025). "In prostate cancer tissue, the PCA3 mRNA level is elevated 60-100 times compared to normal tissue." (PMID 40115018, 2025). "Although studies have demonstrated the utility of monitoring RNA transcripts from PSMA, PCA3, and AR genes for prostate cancer diagnosis, relying solely on these biomarkers may be limiting." (PMID 39859417, 2025). "Furthermore, previous research has reported PRUNE2 as a tumor suppressor that is negatively modulated by PCA3 in prostate cancer." (PMID 41186818, 2025).
prostate carcinoma (continued). "In the future, if PRDX4 is combined with PSA, PAP, and PCA3 for the diagnosis of prostate cancer, it may greatly improve the current limitation of poor PSA specificity and further enhance the sensitivity of diagnosing PCa." (PMID 41445793, 2025). "However, little is known about the role of PCA3 in prostate cancer, except that PCA3 silencing decreases cell growth and survival and induces apoptotic cell death." (PMID 38173042, 2024). "Additionally, PCA3 has been proposed for monitoring the clinical progression of prostate cancer, aiding in therapeutic strategy selection." (PMID 38793175, 2024). "To date, a variety of transcriptional substances in urinary exosomes have been found to play a role in prostate cancer and are potentially attractive in terms of prostate cancer biomarkers, e.g., PCA3, MALAT1, HOTAIR, miR-1290, and miR-375 are some of the more common markers." (PMID 39090720, 2024). "Moreover, developing multiplexed sensors capable of simultaneously detecting multiple biomarkers, such as PCA3 and PSA mRNA, would provide a more comprehensive diagnostic tool, thereby increasing the accuracy and reliability of prostate cancer diagnosis." (PMID 38793175, 2024). "Urinary PCA3 detection is the first urinary-based molecular diagnostic test approved by Food and Drug Administration (FDA) and, nowadays, it is widely used for the diagnosis of prostate cancer." (PMID 37143733, 2023). "Furthermore, a recent meta-analysis involving 46 clinical trials encompassing nearly 12,300 patients utilizing the urine PCA3 test in the diagnosis of prostate cancer was able to reproduce these findings." (PMID 36768533, 2023). "PCA3 has been investigated as a biomarker in prostate cancer." (PMID 36900197, 2023). "TMPRSS2–ERG had an independent, additional predictive value compared to PCA3 and the ERSPC (The European Randomized Study of Screening for Prostate Cancer) risk calculator parameters with respect to the prediction of a biopsy’s Gleason score and clinical tumor stage." (PMID 36672713, 2023). "PCA3 is a lncRNA that exhibits prostate cancer-specific expression." (PMID 37915049, 2023). "Moreover, lncRNA PCA3 has been approved by FDA for clinical diagnosis of prostate cancer, so it is feasible to seek lncRNA in peripheral blood for diagnosis of HCC." (PMID 37735632, 2023). "However, it has not yet been possible to apply this knowledge in biomarker development for routine used in clinical practice, as it occurs with PCA3 in prostate cancer." (PMID 37108589, 2023). "PCA3 lncRNA (Progensa) is already in clinical practice for diagnosis of prostate cancer." (PMID 36428681, 2022). "In urine-derived EVs (CD63-labeled vesicles), both TMPRSS2-ERG and a prostate cancer biomarker, Prostate Cancer Antigen (PCA-3) mRNA, were found, indicating that the mRNA composition of EVs is informative and may give prospective prostate cancer biomarkers." (PMID 36059497, 2022). "Prostate cancer antigen 3 (PCA3), a long non-coding RNA, is upregulated in human prostate cancer." (PMID 35898396, 2022). "Kaplan-Meier curves depicted the association of PCA3, ARV7, and EpCAM in the time to failure of androgen deprivation therapy (ADT) which is defined as from the start of hormone-sensitive phase of ADT to the development of castration-resistant prostate cancer." (PMID 35402423, 2022). "Kaplan-Meier curves demonstrated that PCA3, ARV7, and EpCAM were associated in androgen-deprivation therapy (ADT) failure time which is defined as from the initiation of ADT in hormone-sensitive stage to the development of castration-resistant prostate cancer." (PMID 35402423, 2022). "PCA3 levels in the urine is associated with the extent of metastatic activity of cancerous cells in the prostate, which suggests that PCA3 could be valuable in the diagnosis of prostatic carcinomas." (PMID 36246565, 2022). "Prostate cancer antigen 3 (PCA3) is regarded as a key biomarker in prostate cancer." (PMID 36357869, 2022).
prostate carcinoma (continued). "For early detection of prostate cancer by semi non-invasive method, PCA3 testing may be useful, thus also avoiding unnecessary prostate biopsy." (PMID 36092905, 2022). "Furthermore, the long non-coding intronic RNA, prostate cancer gene 3 (PCA3), has been identified as a highly specific prostate cancer biomarker that is widely expressed in prostate cancer tissues as compared to benign prostate disorders." (PMID 35163550, 2022). "PCA3, one of the most commonly used urine markers for the prognosis of PCa, has been reported to have a sensitivity of 65%, specificity of 73% in detecting prostate cancer, respectively, while AR-V7 positive was detected in a large portion of CRPC." (PMID 35402423, 2022). "The possibility of using lncRNAs as oncological biomarkers has not only been tested, but also turned into a reality with the FDA-approved test PROGENSA® PCA3 assay by Gen-Probe Inc. for prostate cancer diagnosis, which is entirely based on the detection of lncRNA PCA3 in patient urine." (PMID 33767982, 2021). "PCA3, as one of the selected autophagy-related DElncRNAs, expressed highly in PCa cells and tissues and has been identified and applied in clinical practice as a molecular marker of prostate cancer." (PMID 33971627, 2021). "In 2012, PCA3 was FDA-approved as the only urinary biomarker for prostate cancer." (PMID 33799946, 2021). "The one most well-recognized is PCA3, a biomarker for early diagnosis of prostate cancer (PCa)." (PMID 33330574, 2020). "PCA3 is one of the most prostate cancer-specific genes described to date." (PMID 32398974, 2020). "Considering that PCA3 is prostate tissue-specific and highly overexpressed in prostate cancer (PC) tissues compared with benign tissues, it has attracted the interest of academic researchers who validated the potential role of PCA3 as a biomarker for PC diagnosis." (PMID 33267888, 2020). "The method provided a high specificity for PCA3 gene in LNCaP prostate cancer cell line." (PMID 32398974, 2020). "For example, lncRNA PCA3 is highly expressed in prostate cancer." (PMID 33231563, 2020). "For example, the lncRNA PCA3 was found to be useful for the early diagnosis of prostate cancer." (PMID 32731343, 2020). "We propose multiplexing this assay with our previously identified aggressive disease markers, as well as existing clinical biomarkers such as Prostate cancer antigen 3 (PCA3), TMPRSS2:ERG (T2:ERG), etc. to assist in the management of prostate cancer especially in low‐risk cohorts." (PMID 32614141, 2020). "Consequently, elevated PCA3 level during prostate cancer progression has become a widely targeted biomarker for detection." (PMID 32999292, 2020). "Thus, PCA3 is a prostate cancer-specific lncRNA biomarker, overexpressed in prostate cancer tissues and in HGPIN." (PMID 31366128, 2019). "The first reported prostate tissue-specific and prostate cancer-associated, long non-coding (lnc) RNAs were differential display 3 (DD3)/(PCA3) and a prostate cancer gene expression marker 1 (PCGEM1); however, PCA3 was found to be over-expressed in virtually all prostate cancers." (PMID 31013716, 2019). "PCA3 is the most specific prostate cancer (PCa) molecule identified to date." (PMID 31762940, 2019). "PCA3 is detectable in urine and its clinical utility was explored in several studies: the clinical sensitivity and specificity of urinary PCA3 evaluation for prostate cancer detection are 58–82% and 72–79%, respectively." (PMID 31366128, 2019). "Exosomes from urine possess mRNA-encoding protein prostate cancer-associated 3 (PCA3) and the transmembrane protease serine 2 (TMPRSS2)–erythroblast transformation-specific (ETS)-related gene (ERG) fusion product, an entity over-expressed in prostate cancer." (PMID 30699987, 2019).